GLS (glutaminase)
Diseases named in the same sentence as GLS in open-access papers (continued):
Sharing a sentence is not in itself a finding about the gene and the disease.
tumor (continued). "ASNS, GLS, and GOT2 encode ASNS, GLS, and GOT2, respectively, which are key enzymes in asparagine synthesis and are all required for tumor growth and metastasis, prompting the hypothesis that asparagine synthesis is required for SOX12-mediated CRC progression." (PMID 30858360, 2019). "Moreover, CB-839, which is a selective inhibitor of glutaminase, was shown to have potent anti-tumour activity both in vitro and in vivo TNBC models." (PMID 31052256, 2019). "In addition, glutaminase inhibition prevents ammonia accumulation and reduces ammonia-induced autophagy, leading to a metabolic crisis that sensitizing tumour cells to death." (PMID 30646605, 2019). "However, as discussed in Section 7, the physiological responses to glutaminase inhibition are likely to be different from glutamine deprivation in tumor cells." (PMID 31212591, 2019). "Expression of glutaminase was determined in 120 cartilage tumours by immunohistochemistry." (PMID 29576625, 2018). "Both agents specifically inhibit the GLS isoenzyme (both splice variants KGA and GAC) by binding to the protein at distinct allosteric sites and have demonstrated antitumor activity in multiple tumor types." (PMID 28950000, 2017). "In order to test whether glutaminase inhibition by CB-839 can result in reduced tumor volume in vivo, we carried out mouse xenograft studies using MPNST serial transplant tumors." (PMID 29212209, 2017). "The TN clusters (TN and TN+Her2) include proliferative proteins (MCM3 and 5), translation related proteins (RCL1, MRPS27, EIF2S2 and EEF1G) and metabolic enzymes (glutaminase and hexokinase 2), which reflect the higher dependence on glutamine and glucose of TN versus the other tumours." (PMID 26725330, 2016). "Glutaminase is highly expressed in rapidly growing tumour cells." (PMID 27825361, 2016). "Indeed, treating tumor cells with an antisense glutaminase mRNA induces apoptosis under oxidative stress." (PMID 27462863, 2016). "As the BPTES treatment displayed minimal effect on tumor growth from parental cells, we next focused to validate whether targeting glutamine metabolism is efficient to inhibit resistant tumor growth using a different glutaminase inhibitor, L-DON." (PMID 26139106, 2015). "Therefore, we hypothesize that tumor cells with low GLS expression, due to reduced glutaminase activity, increase the glutamine in the TME, thereby alleviating glutamine deficiency in immune cells." (PMID 40308578, 2025). "Furthermore, dual metabolic modulation-such as pairing IDO1 degraders with adenosine pathway inhibitors or glutaminase blockers-may address tumor plasticity." (PMID 40894232, 2025). "Consequently, it can be hypothesised that elevated GLS expression in tumor cells may be indicative of increased immune cell infiltration within the tumour microenvironment and a more favorable response to antitumor immunotherapy." (PMID 41050056, 2025). "However, GLS inhibition was found to impair CD8 + T-cell activation in STK11-/LKB1-deficient lung cancer, and the use of CB-839 to inhibit CD8 + T-cell expansion negatively impacted tumor therapy." (PMID 40598593, 2025). "Using drugs that target the unique metabolic dependencies of specific tumors (e.g., OXPHOS inhibitors, glutaminase inhibitors) could slow tumor growth and potentially reduce the tumor’s nutrient consumption, indirectly “freeing up” metabolites in the TME for use by CAR T cells." (PMID 41471036, 2025). "Genetic ablation of glutaminase (GLS), a critical enzyme that boosts conversion into glutamate, in tumor cells could lead to increased glutamine concentration and improved T-cell infiltration within tumor nests." (PMID 39107856, 2024). "In addition, the glutaminase inhibitor CB839 effectively inhibited tumor growth of TNBC cells." (PMID 39027328, 2024).
tumor (continued). "However, they found that using a non-tumor cell-specific glutaminase inhibitor in combination with anti-PD-1 severely impeded CD8+ T cell clonal expansion and anti-tumor functions, and anti-PD-1 efficacy was dependent on intact CD8+ T cell glutaminase activity." (PMID 37842241, 2023). "Moreover, GCN5L1 acts as a tumour suppressor by regulating glutaminase acetylation and activity." (PMID 35538890, 2022). "Moreover, limiting glutaminase activity results in a decreased growth rate in tumour cells." (PMID 35715635, 2022). "Enhancement of glutaminase (GLS) K311 succinylation may promote tumor cell survival and tumor growth by increasing glutaminolysis and the production of nicotinamide adenine dinucleotide phosphate (NADPH) and glutathione through counteracting the oxidative stress." (PMID 34788852, 2022). "As the effect of glutaminase inhibitors in clinical trials has been variable, methods for metabolic profiling of tumor tissue from test subjects could help identify predictive biomarkers or other traits that can contribute to discriminate between responding and non-responding patients." (PMID 34564393, 2021). "Another study showed that combination treatment of GLS inhibitors with ICIs significantly decreased tumor volume in an ICI-resistant-tumor mouse model, and the possible underlying mechanism may via enhancing CD8+ T cell activities and by decreasing ARG1-expressing myeloid cells." (PMID 33514004, 2021). "In addition, glutamine produces glutamate due to the action of glutaminase (GLS), which then enters the tricarboxylic acid cycle in the form of alpha‐ketoglutarate to produce ATP, thereby providing energy for the rapid proliferation of tumor cells." (PMID 32162845, 2020). "Furthermore, downregulation or inhibition of GLS has slowed the proliferation of these tumor cells." (PMID 32937954, 2020). "However, whether the functions of glutaminase is tumorigenic or tumor suppressive remains controversial, especially from the view of isoenzymes." (PMID 33194749, 2020). "The expression of glutaminase (GLS) (a marker of glutaminolysis) was high in 71% of the primary and 55% of the recurrent cases, suggesting that glutaminolysis is rather implicated in the early steps of tumor development, using glutamine as an alternative bioenergetic substrate in RMS cells." (PMID 32709151, 2020). "Since tumour cells are addicted to glutamine and often show an overexpression of glutaminase, we hypothesize that the antitumoral mechanism of metformin could be ascribed to inhibition of GLS and reduction of ammonia and ammonia-induced autophagy." (PMID 30646605, 2019). "Its functions in the metabolic rewiring of tumor cells are poorly understood, but it might be involved in glutamine metabolism as it inhibits GLS and in OXPHOS and TCA regulation, as it decreases SDH activity by targeting both SDHA and SDHB and it inhibits PDC." (PMID 30197878, 2018). "In addition, beyond the use of xCT/SLC7A11 expression as a marker for glutaminase inhibitor responsiveness, raising tumor cystine levels might also be a way to induce or enhance glutamine addiction." (PMID 28826492, 2017). "We then reasoned that if the serine pathway was so critical to support tumor cell proliferation when the metabolism of Gln was inhibited, serine starvation could have detrimental effects on the in vivo tumor growth when combined to the inhibitor of glutaminase BPTES." (PMID 26625201, 2016). "Moreover, the engineered E. coli with l-asparaginase biosynthesis gene has the potential pharmaceutical and industrial application, since it can produce the glutaminase free anti-tumour enzyme at high rates and can avoid the complex down streaming process associated with conventional bioprocess." (PMID 26206135, 2015).
tumor (continued). "Consistent with in vitro findings, GLS silencing significantly enhanced radiosensitivity in LUAD subcutaneous xenograft models, as evidenced by reductions in tumor volume and weight following radiotherapy." (PMID 40308578, 2025). "The glutamine metabolism requires glutaminase (GLS) to convert it to glutamate, which promotes the growth of tumor cells through the reprogramming of glutamine metabolism that occurs in tumor cells." (PMID 40696413, 2025). "In this study, we sought to explore the potential impact of changes in the expression of cuproptosis-related genes, GLS and PDHA1, on the tumor microenvironment and immune response." (PMID 41050056, 2025). "Paired comparisons further confirmed the upregulation of FDX1, DLAT, PDHA1, GLS, and CDKN2A in tumor samples." (PMID 40410601, 2025). "Together, these results demonstrate that inhibition of GLS activates the immunoproteasomes and enhances the MHC‐I antigen presentation in tumor cells." (PMID 39482885, 2025). "Tumour cells deplete critical amino acids like tryptophan, arginine, and glutamine in the TME through enzymes such as IDO, arginase, and glutaminase, which suppress immune activity." (PMID 40175681, 2025). "On the glutamine axis, iCCA cells frequently overexpress glutaminase-1 (GLS1), and preclinical work (e.g., the GLS1 inhibitor CB-839) has shown that suppression of glutamine metabolism reduces malignant phenotypes and may sensitize tumours to immunotherapeutic intervention." (PMID 41394868, 2025). "Glutaminase (GLS) inhibitors, such as CB-839 (telaglenastat), and inhibitors of serine and glycine synthesis pathways have shown potential in impairing tumor growth by disrupting critical metabolic processes." (PMID 40469185, 2025). "Increased expression of glutaminase (GLS1) and the glutamine transporter SLC1A5 has been observed in tumor tissues, suggesting their potential utility as metabolic biomarkers for early GC detection." (PMID 41244835, 2025). "Succinylation of GLS K311 activates GLS, increasing NADPH and GSH production to fight oxidative stress ROS generation and apoptosis, tumor cell proliferation, and tumor growth." (PMID 40865948, 2025). "For example, the upregulation of glutaminase (GLS) in tumor cells leads to the production of glutamate, which can suppress T cell activity and promote tumor immune evasion." (PMID 41163383, 2025). "SLC7A11 gene expression is positively correlated with other amino acid transporters like SLC3A2, SLC1A5, GLS, and the infiltration of neutrophils and macrophages, suggesting that SLC7A11 plays a coordinated role in metabolic regulation and tumor immunity." (PMID 39973065, 2025). "In this study, scRNA‐seq results revealed that the expressions of GLS, PPP1R13L, MYB, and YAP1 were significantly elevated in tumor epithelial cells." (PMID 41152153, 2025). "Utilising these findings, we have further elucidated the cell-specific expression patterns of GLS and PDHA1 in the tumour microenvironment of lung squamous carcinoma by employing single-cell sequencing technology." (PMID 41050056, 2025). "Firstly, Western blot analysis revealed that compared to the Vector+PBS + PBS group, the RPS27-RPS24 + PBS + PBS group of mice showed a significant increase in the expression levels of RPS27-RPS24, GLS, FDX1, LIAS, and Lipoy-DLAT proteins in tumor tissues." (PMID 40280903, 2025). "Administering a combination of a glutaminase inhibitor and 5FU/DDP to mice with TIGAR-overexpressing ESCC cell grafts and patient-derived tumor grafts led to significant suppression of tumor growth compared to using chemotherapy alone." (PMID 40277923, 2025). "In order to comprehend the molecular physiological functions of the GLS and PDHA1 genes in the LUSC tumour microenvironment, their localization in LUSC was determined." (PMID 41050056, 2025). "Forced clustering of GLS1, using constitutively clustering mutants, restored high GLS activity, promoted apoptosis, and suppressed ccRCC tumor growth in vivo." (PMID 41165759, 2025).
tumor (continued). "Inhibiting enzymes along this axis, glutaminase (GLS) and glutamate dehydrogenase (GDH), has emerged as a strategy to suppress tumor growth and alter immune responses." (PMID 40931345, 2025). "Through a multi-dimensional approach, we demonstrate that GLS inhibition enhances radiosensitivity by promoting ferroptosis and reprogramming the TME to potentiate anti-tumor immunity." (PMID 40308578, 2025). "Glutaminase (GLS), a key enzyme for glutamine metabolism, has been found to regulate glutamine availability within tumor microenvironment (TME)." (PMID 40308578, 2025). "Special focus is given on the glutaminase isoform, GLS1 (kidney type glutaminase), as the other isoform GLS2 (Liver type glutaminase) acts as a tumour suppressor in some conditions." (PMID 38939098, 2024). "Upregulation of GLS expression promotes glutamine depletion in tumor cells, leading to HIF-1α activation and IL-23 secretion by TAMs, which can inhibit the tumor-killing effect of cytotoxic lymphocytes." (PMID 39539540, 2024). "CB-839, a novel antagonist of GLS, inhibits the utilization of glutamine by tumor cells, which, in turn, increases the availability of glutamine in the TME to promote the anti-tumor effects of immune cells." (PMID 39227970, 2024). "Conversely, genes like CDKN2A, GLS, MTF1, and SLC31A1 exhibited marked upregulation in the tumor, suggesting distinct roles in the pathophysiology of the disease." (PMID 38898987, 2024). "Levels of GLS have been shown to be pivotal in glutaminolysis and crucial for GBM cell survival and tumour growth." (PMID 39408757, 2024). "GLS and GDH were robustly expressed in PTC cells compared with FTC cells, which was consistent with the IHC results from tumor specimens." (PMID 38386265, 2024). "In Gln-addicted HCC cells, a combinational treatment with CB-839 (glutaminase inhibitor) and V-9302 (an inhibitor targeting the ASCT2 transporter) produced better tumour inhibition than monotherapy with CB-839 alone." (PMID 38699532, 2024). "Glutamine enters tumor cells via specific transporters such as SLC1A5, and is then catalyzed to produce glutamate through glutaminase (GLS)." (PMID 38970690, 2024). "The use of a glutaminase antagonist, JHU083, effectively inhibited tumor growth in a variety of solid tumor models and significantly improved mouse survival." (PMID 38581001, 2024). "IHC staining showed that the expression level of Ki‐67 and WDR76 was decreased in xenograft tumours induced by LRPPRC knockdown in MDA‐MB‐231 cells, while the inhibitor of glutaminase BPTES further lowered the level of Ki‐67." (PMID 38372449, 2024). "GLS correlates with tumor growth and proliferation, while GLS2 can function as a context-dependent tumor suppressor." (PMID 38929183, 2024). "It has been reported that the expression of CDKN2A, GLS and LIPT1 is positively correlated with the abundance of CD8+T cells and neutrophils and CDKN2A expression positively correlated with the degree of tumor infiltration, which was in line with our study." (PMID 36843949, 2023). "We found that FDX1, DLD, PDHA1, MTF1, GLS, and CDKN2A showed differential expression levels between normal and tumor tissues." (PMID 37711156, 2023). "Double IHC disclosed that in some plurimetabolic PDX the two markers were co-expressed by the same tumor cells, whereas in others MCT4 and GLS were mostly expressed by different cells which, however, clustered in the same spatial area of the tissue." (PMID 36925926, 2023). "The expression level of CRGs with CNV amplification was higher in CRC samples compared to normal samples (e.g., GLS and PDHA1), while the expression level of LIAS was relatively decreased in tumor samples." (PMID 37006250, 2023). "Astonishingly, the pro-tumorigenic effect, assessed as tumor volume and the number of lung metastases, was more pronounced when GLS2 overexpression was accompanied by GLS knockdown." (PMID 38067269, 2023).
tumor (continued). "Blockade of glutamine metabolism by the use of the glutaminase antagonist, JH083, suppresses the metabolic reprogramming of cancer cells but enhances the anti-tumor CD8+ T cells and increases tumor infiltration." (PMID 36644500, 2023). "The lncRNAs affect the process of tumor metastasis by regulating the cell cuproptosis sensitivity such as CDKN2A, GLS and MTF1." (PMID 37745054, 2023). "In this analysis, we found that the expression of FDX1, GLS, and CDKN2A increased when the tumor progressed from the T2 stage to the T3 stage." (PMID 37711156, 2023). "Tumor cells provide ATP through aerobic glycolysis, the pentose phosphate pathway (PPP), glutaminase (GLS) decomposition, one‐carbon metabolism, and de novo fatty acid synthesis, which produce a series of biological macromolecules to promote proliferation." (PMID 36994237, 2023). "It is reported that in many tumor cell lines including B lymphoma, the metabolism of glutamine is modulated by MYC via increasing the expression of GLS." (PMID 37367892, 2023). "SLC7A5 has been reported to be overexpressed in TNBC due to its glutamine transporting activity to tumor cells for energy production—TNBC is thus glutamine dependent and requires glutaminase for its catabolism." (PMID 37900178, 2023). "Difference analyses showed that 7 of 10 CRGs were dys-regulated in tumor samples compared with those in normal samples, among which LIPT1, PDHA1, GLS and CDKN2A were up-regulated, and FDX1, DLD and MTF1 were down-regulated." (PMID 37333810, 2023). "Among them, the expression levels of CDKN2A, GLS and LIPT1 were significantly upregulated whereas the expression levels of DLAT, DLD, FDX1, MTF1 was significantly downregulated in tumor samples." (PMID 37072493, 2023). "Glutaminase GLS2 is an enzyme that metabolizes glutamine, one of the main sources of energy and building blocks in tumor cells." (PMID 38067269, 2023). "In tumor tissues, the abundance of CDKN2A and MTF1 were higher, as well as the levels of DLD, FDX1, GLS, LIPT1 and PDHB were down-regulated." (PMID 37662947, 2023). "GAC is the predominant GLS isoform in a variety of tumor cells and is demonstrated to be correlated with tumor growth 10-13." (PMID 35864951, 2022). "Here, we report that inducible genetic deletion of glutaminase (GLS) specifically in host endothelium, GLSECKO, impairs tumor growth and metastatic dissemination in vivo." (PMID 36381236, 2022). "Glutaminase KD with shRNAs of MDA-MB-231 and SUM-159PT as tumour xenografts in mice led to similar tumour regression in vivo." (PMID 36290817, 2022). "Inhibition of GLS with CB-839, or of glutamine metabolism broadly with JHU083 or DRP-104 (Sirpiglenastat, another pro-drug of DON), restores balance between tumor and T-cell glutamine utilization." (PMID 36465373, 2022). "Loss of GLS was confirmed by qRT-PCR and Western blot analysis in isolated lung microvascular ECs, as well as colocalization of anti-GLS and anti-CD31 immunofluorescence in tumor sections." (PMID 36381236, 2022). "IHC results revealed that the high ASCT2, GLS, and SNAT2 expression in the xenograft tumor was correlated with high glutamine uptake in the area." (PMID 35365739, 2022). "In human HCC tumours compared to adjacent tissue, there were variable levels of mTORC1 activation, GCN5L1 levels and glutaminase activity." (PMID 35538890, 2022). "CDKN2A, GLS, LIPT1, and PDHA1 were up-regulated in tumor samples, and FDX1, DLD, MTF1 were down-regulated in tumor samples." (PMID 36176287, 2022). "Subsequently, we detected the expression of these CRGs in tumor and normal samples and found that 6 genes, FDX1, LIAS, DLD, DLAT, PDHB and MTF1, were significantly downregulated in tumors, while 2 genes, GLS and CDKN2A, were significantly upregulated." (PMID 36246586, 2022).